ARID2 (AT-rich interaction domain 2)
Diseases named in the same sentence as ARID2 in open-access papers (continued):
Sharing a sentence is not in itself a finding about the gene and the disease.
breast carcinoma (6 papers, 2021 to 2025). "Similar to the BAF subfamily, the mutations in auxiliary subunits in the PBAF subfamily, such as PBRM1 and ARID2, are frequently observed in breast cancers." (PMID 41278204, 2025). "For MPD, frequent mutations in chromatin remodeling genes, such as lysine methyltransferase 2C (KMT2C) and AT-rich interaction domain 2 (ARID2), are well-documented, aligning with its strong association with underlying breast carcinoma." (PMID 40230781, 2025). "So far, there are few reports on the relationship between ARID2 and breast cancer, and further research is needed to determine the role and mechanism of ARID2 in breast cancer." (PMID 38365747, 2024). "Further investigation on the role of ARID2 in breast cancer would be of great interest." (PMID 41278204, 2025). "For all I know, so far there are no reports about the association between ARID2 and breast cancer." (PMID 33592583, 2021). "A decrease in ARID2 expression is frequently found in non-luminal breast cancer subtypes but ARID2 is a predictor of poor survival in ER-positive breast cancer patients." (PMID 41278204, 2025). "Research indicates that there is a frequent occurrence of low expression of ARID2 in non-luminal breast cancer subtypes." (PMID 38365747, 2024). "Low mRNA expression of ARID2 (p=0.0035), ARID4A (p=0.0349), JARID1A (p=0.0473), JARID1D (p=0.0322) and high mRNA expression of JARID1B (p=0.0067), JARID1C (p=0.0407) were interrelated with worse OS in grade II breast cancer patients." (PMID 33592583, 2021). "Low mRNA expression of ARID1A (p=0.0096), ARID2 (p=0.0066), ARID3B (p= 0.000024), ARID5A (p=0.0435), ARID5B (p=0.0022), JARID1A (p=0.0044), JARID2 (p=0.0463) were interrelated with worse OS in grade III breast cancer patients." (PMID 33592583, 2021). "Our research demonstrated low ARID2 expression was frequent in no-luminal breast cancer type and forecasted poor survival in all breast cancer patients and ER+ breast cancer patients by K-M plotter analysis." (PMID 33592583, 2021). "The low mRNA expression of ARID1B (p=0.0023), ARID2 (p=0.0439), ARID4A (p=0.0056), ARID4B (p=0.0317), ARID5B (p=0.00054), JARID1D (p=0.043), JARID2 (p=0.0068) were interrelated with poor survival in breast cancer patients with negative lymph node." (PMID 33592583, 2021). "The expression of ARID1A, ARID1B, ARID2, ARID3A, ARID4A, and ARID4B in no-luminal subtypes was lower than luminal subtypes, however, ARID3C, ARID5A, and JARID2 mRNA expression were higher in no-luminal subtypes of breast cancer tissues." (PMID 33592583, 2021).
developmental delay (6 papers, 2018 to 2025). "The main clinical features of ARID2-RD are developmental delay, speech disorders, intellectual disability (ID), behavior problems, short stature, and various dysmorphic and ectodermal features." (PMID 40044822, 2025). "Sparse scalp hair (5/8, 63%) and global developmental delay (4/8, 50%) were seen in a majority of ARID2 patients." (PMID 34205270, 2021). "Heterozygous ARID2 mutations have been linked to Coffin–Siris syndrome 6 (CSS6), a rare genetic intellectual disorder characterized by a mild to severe developmental or cognitive delay." (PMID 39857780, 2025).
gastric cancer (6 papers, 2016 to 2025). A primary or metastatic malignant neoplasm involving the stomach. "Furthermore, the expression of ARID2 and its family members is lost during gastric cancer progression, but the effect of ARID2 on tumor progression is weaker than that of ARID1A." (PMID 27270314, 2016).
leukemia (6 papers, 2017 to 2025). A malignant (clonal) hematologic disorder, involving hematopoietic stem cells and characterized by the presence of primitive or atypical myeloid or lymphoid cells in the bone marrow and the blood. "Additionally, the loss of ARID2 leads to reduced differentiation of early lymphocytes and increased the likelihood of leukemia development." (PMID 40342423, 2025). "For example, in mice, Arid2 has a dual role, being suppressed to enhance initial leukemogenesis, but being necessary during leukemia maintenance." (PMID 36941700, 2023). "In addition to Myc and Bcl2, other tumor-promoting genes such as Eef2 and Myh10 were upregulated in leukemia cells, whereas tumor suppressors such as Ikzf1, Ikzf2, Arid1b, Arid2, Samhd1, Bach2, and Myo18b were downregulated." (PMID 34907175, 2021). "High expression of ARID2, JMJD1C, MBNL1, MEF2C, or RUNX2 alone is associated with at least one indicator of poor prognosis in ALL patients, and CPEB2, MBNL1, RUNX2, and ZEB2 are all specifically overexpressed in MLL-FP leukemias." (PMID 28076791, 2017). "The ARID2-mediated PBAF plays an important role in HSCs and prevents leukemia." (PMID 40342423, 2025). "Full transformation associates with transcriptional upregulation of oncogenes such as Myc or Bcl2, downregulation of tumor suppressors such as Ikzf1 or Arid2, and major IL-7R signaling upregulation (involving JAK/STAT5 and PI3K/mTOR), required for leukemia cell viability." (PMID 34907175, 2021).
lung adenocarcinoma (5 papers, 2021 to 2023). A carcinoma that arises from the lung and is characterized by the presence of malignant glandular epithelial cells. "Somatic mutations of the chromatin remodeling gene ARID2 are observed in ∼7% of human lung adenocarcinomas (LUADs)." (PMID 34858604, 2021). "Researchers have found that during the occurrence and development of lung adenocarcinoma in humans and mice, the expression level of ARID2 gradually decreases." (PMID 38023196, 2023). "For this, we made use of a GR activity score (explained above) and the lung adenocarcinoma dataset from TCGA (91/877 tumours harboured SWI/SNF mutations; SMARCB1 18.09%; SMARCC2 9.52%, SMARCD2 6.66%, SMARCD3 1.90%, ARID1A 29.52%, ARID2 31.42%, SMARCE1 2.85%)." (PMID 34272384, 2021). "Moreover, TCGA gene expression profiling datasets of lung squamous cell carcinoma (LSCC) and lung adenocarcinoma tumor samples were utilized to validate the pattern of USP2/ARID2 mRNA expression." (PMID 36567903, 2022).
adenoma (4 papers, 2017 to 2021). A neoplasm arising from the epithelium. "As with ARID2, the TSG and candidate drivers of colorectal adenomas ARID1A, and ARID1B are frequently mutated in MSI tumours including adenomas." (PMID 34843512, 2021). "Among the most interesting driver genes identified in the present MSH3-deficient adenomas are ACVR2A and ARID2." (PMID 34843512, 2021). "We found that ARID2 expression was progressively decreased from AAH, adenoma, to adenocarcinoma in this model." (PMID 34858604, 2021).
cervical cancer (4 papers, 2019 to 2024). A primary or metastatic malignant neoplasm involving the cervix. "To identify the effect of ARID2 in cervical cancer, we knocked down ARID2 expression in CaSki cells using targeting siRNAs, and the siRNA interference efficiency was determined by qRT-PCR and immunoblotting analyses." (PMID 31595161, 2019). "The AT-rich interactive domain (ARID2)-containing family of DNA-binding proteins was verified to be a direct target of miR-155-5p and responsible for the progression of cervical cancer." (PMID 31595161, 2019). "In conclusion, these data demonstrate that exosomal miR-155-5p suppresses ARID2 expression via ERCC5-NF-κB signaling to promote invasion in cervical cancer." (PMID 31595161, 2019). "HIV-infected T-cell-derived miR-155–5p is transferred directly from HIV-1-infected T cells to cervical cancer cells via exosomes while activating the NF-κB signaling pathway by reducing the expression of its target gene ARID2, thus promoting the invasion of cervical cancer cells." (PMID 38988816, 2024). "MiR-155-5p in exosomes isolated from HIV-infected T cells facilitated the proliferative, migrative, and invasive abilities of cervical cancer cells, which may be mediated through the AT-rich interaction domain 2 (ARID2)-ERCC5-NF-κB pathway." (PMID 35024437, 2022). "ARID2 expression could be down-regulated in cervical cancer cells by miR-1247-3p at both the mRNA and protein levels." (PMID 31595161, 2019). "Most importantly, we determined that miR-155-5p was directly transferred from HIV-1-infected T cells to cervical cancer cells via exosomes and promoted invasion by decreasing the expression of its target gene ARID2 to activate the ERCC5-NF-κB signaling pathway." (PMID 31595161, 2019).
Coffin-Siris syndrome 6 (4 papers, 2020 to 2025). Any Coffin-Siris syndrome in which the cause of the disease is a mutation in the ARID2 gene. "This is the case for de novo heterozygous ARID2 mutations, which have been linked to the Coffin-Siris syndrome 6 (CSS6), a rare genetic intellectual disorder characterized by a mild to severe developmental or cognitive delay." (PMID 32977645, 2020). "Coffin-Siris syndrome 6 is caused by heterozygous mutations in ARID2." (PMID 38822427, 2024). "Mutations in the ARID2 gene is the cause for Coffin-Siris syndrome 6 (CSS6)." (PMID 35813374, 2022).
cutaneous melanoma (4 papers, 2019 to 2025). A primary melanoma arising from atypical melanocytes in the skin. "In conclusion, our work presents cutaneous melanoma patients with ARID2 mutation as potential candidates for ICI therapy and suggests the possibility of improved overall tumor prognosis." (PMID 38341515, 2024). "This study highlighted that cutaneous melanoma patients with the ARID2 mutation showed a distinct profile with a significant association with immunotherapy response markers and survival outcomes." (PMID 38341515, 2024). "ARID2 mutations were more prevalent in cutaneous melanoma compared to ARID1A (11.0%: n = 451 vs 2.8%: n = 113), with concurrent ARID1A/ARID2 mutation in 1.1% (n = 46) of samples." (PMID 38341515, 2024). "In this study, we assessed a cohort of cutaneous melanoma patients with ARID mutations to identify the ARID2 mutation’s impact on prognosis and response to ICI treatment for cutaneous melanoma patients." (PMID 38341515, 2024).
gastric adenocarcinoma (4 papers, 2016 to 2025). "The ARID2 gene was mutated at a frequency of 5.3% in 514 gastric adenocarcinoma cases." (PMID 27270314, 2016).
multiple myeloma (4 papers, 2022 to 2024). "In addition, a poor prognosis and chemoresistance of multiple myeloma patients were believed to be closely related to the ubiquitination of ARID2." (PMID 36567903, 2022). "In contrast, POM can suppress the c-MYC gene via proteasome-dependent degradation of AT-rich interaction domain 2 (ARID2), which is not a target molecule of LEN, suggesting that POM might be effective for a part of LEN-resistant myeloma cells." (PMID 38004369, 2023).
renal fibrosis (4 papers, 2020 to 2022). A final common manifestation of a wide variety of chronic kidney diseases characterized by glomerulosclerosis and tubulointerstitial fibrosis. "The differential effects of Arid2-IR in renal fibrosis and inflammation suggest that Arid2-IR may be a downstream mediator of Smad3 in renal inflammation because mice null for Smad3 are protected against Smad3-mediated fibrosis and NF-κB-driven inflammation in a number of renal diseases." (PMID 32295041, 2020). "Further investigation revealed that Arid2-IR stimulates the NF-κB-dependent renal inflammatory pathways without effect on TGF-β1/Smad3-mediated renal fibrosis in vitro and in vivo." (PMID 32295041, 2020). "Arid2-IR shares a similar mechanism with Ptprd-IR that overexpression of Arid2-IR may promote TGF-β1-, IL-1β-induced NF-κB-driven inflammation without affecting TGF-β/Smad3-mediated renal fibrosis." (PMID 34054586, 2021).
BAFopathy (3 papers, 2021 to 2025). Disorder caused by mutations in the various subunits composing the BAF complex. "Typical CSS, which is also referred to as BAFopathy, is caused by variants in the subunit of BAF complex, including ARID1A (OMIM#603024), ARID1B (OMIM#614556), SMARCA4 (OMIM#603254), SMARCB1 (OMIM#601607), ARID2 (OMIM#609539), and SMARCE1 (OMIM#603111)." (PMID 35938035, 2022).
Intellectual disability (3 papers, 2021 to 2025). "In Family 35, we initially reported a 1.8-Mb inversion involving ARID2 in a male with intellectual disability and delayed motor development." (PMID 38776926, 2024).
pancreatic cancer (3 papers, 2015 to 2022). "Though mutations in ARID2 have been described in pancreatic cancer, no mutations of ARID2 have been previously reported in primary PanNETs and liver metastases." (PMID 36140756, 2022).
acral melanomas (2 papers, 2022 to 2023). "For example, ARID2 mutations seem more frequent in acral melanomas, but their significance remains unknown." (PMID 37373134, 2023). "Also, it has been reported that subungual melanoma harbors more distinct genomic alterations including CARD11, ARID2, ARID1A, ARID1B, PTPRB, and PTPRK genes, compared with acral melanoma." (PMID 35484605, 2022).
cholangiocarcinoma (2 papers, 2024 to 2025). A carcinoma that arises from the intrahepatic biliary tree (intrahepatic cholangiocarcinoma) or from the junction, or adjacent to the junction, of the right and left hepatic ducts (hilar cholangiocarcinoma). "Mutations in ARID2 showed increased enrichment of four of five signatures for cholangiocarcinoma (CHOL)." (PMID 38358974, 2024).
head and neck cancer (2 papers, 2017 to 2022). A primary or metastatic malignant neoplasm affecting the head and neck. "Nonsense mutation of ARID2 p.R1273X in our study has been reported in esophageal and head/neck cancers." (PMID 28179590, 2017).
medulloblastoma (2 papers, 2020 to 2022). A malignant, invasive embryonal neoplasm arising from the cerebellum. "Two orange cluster processes (GO terms covalent chromatin modification and ATP-dependent chromatin remodeling) stand out, as genes involved in chromatin regulation like Arid2, are known to be mutated in medulloblastoma." (PMID 35535520, 2022). "Importantly, the correlation coefficient of the subunit ARID2 in Medulloblastoma was found to be reversed as that in MEF and indicates the different ways of MYC dependent regulation possibilities on a gene." (PMID 31932624, 2020).
myelodysplastic syndrome (2 papers, 2023 to 2024). A clonal hematopoietic disorder characterized by dysplasia and ineffective hematopoiesis in one or more of the hematopoietic cell lines. "Moreover, sequencing studies carried out on AML and/or myelodysplastic syndromes (MDS) have found recurrent deleterious mutations in SWI/SNF genes including ARID2, ARID1A and ARID1B, SMARCA2, and SMARCA4." (PMID 36941700, 2023).
oral cancer (2 papers, 2022). "MiR-155-5p, a well-known oncogenic miRNA, promotes oral cancer progression by suppressing the chromatin remodeling gene ARID2." (PMID 36224588, 2022). "Several authors reported that miR-155-5p promotes the progression and surveillance of oral cancer by modulation of different targets such as the chromatin remodeling gene ARID2 and TP53INP1 that confirms resistance to 5-Fluorouracil." (PMID 36531016, 2022).
squamous carcinoma (2 papers, 2021 to 2025). "Mutations in other genes, such as CDKN2A and ARID2, were rare in normal skin but common in squamous cell carcinoma, implying that they undergo selection comparatively later in tumor evolution." (PMID 41309580, 2025). "Finally, ARID2 mutations, which disrupt the SWI/SNF chromatin remodeling complex, and gain-of-function mutations in the RTK-RAS-MAPK pathway were enriched specifically in squamous cell carcinomas." (PMID 41309580, 2025). "Additionally, ARID1A and ARID2 mutations were more frequently found in males, SMARCA4 was more frequently mutated in patients with adenocarcinoma, and the ARID1B mutation was more frequently found in patients with squamous carcinoma, which were all statistically significant." (PMID 34512623, 2021).
anaplastic thyroid cancer (1 paper, 2020). "Some of these genes may be of particular interesting in the thyroid; for instance, Arid2 was shown to be mutated in poorly differentiated and anaplastic thyroid cancer, and Akirin 2 is emerging as a novel player in the NF-κΒ-driven immune/inflammatory response." (PMID 32961913, 2020).
autism (1 paper, 2024). Persistent deficits in social interaction and communication and interaction as well as a markedly restricted repertoire of activity and interest as well as repetitive patterns of behavior. "Regulatory inference using the Genie3 algorithm identified direct regulation of IGF1 by SIK1, MFRP, CHD7, NIPBL, EXOC5, and ARID2, with SIK1 and SPARCL1 significantly downregulated in autism brain organoids, potentially affecting IGF1 expression." (PMID 39376742, 2024).
autosomal dominant cerebellar ataxia (1 paper, 2025). A clinically and genetically heterogeneous group of neurodegenerative diseases characterized by a slowly progressive ataxia of gait, stance and limbs, dysarthria and/or oculomotor disorder, due to cerebellar degeneration in the absence of coexisting diseases. "However, the MVP classifier is also showing that cases with an autosomal dominant cerebellar ataxia, deafness, and narcolepsy (ADCADN) (OMIM #604121) episignature are responding on the ARID2 episignature based on the MVP score being higher than 0, some as high as 0.75." (PMID 40044822, 2025).
Beck-Fahrner syndrome (1 paper, 2025). "Here, we observed that ARID2 clustered in a hypermethylation branch close to Beck-Fahrner syndrome (BEFAHRS; TET3) and Kabuki syndrome (KMT2D)." (PMID 40044822, 2025).
behavioral disorders (1 paper, 2025). "These neurodevelopmental syndromes share features with ARID2-RD, such as hypotonia, psychomotor delay, speech disorders, ID, and behavioral disorders." (PMID 40044822, 2025).
breast tumors (1 paper, 2013). "For example, the exploration of the SWI/SNF complex in breast tumors revealed that ARID1A tends to be mutated in samples where neither SMARCA4, ARID2 nor SMARCA2 are mutated." (PMID 24063517, 2013).
chordoma (1 paper, 2025). Chordomas are rare malignant tumors arising from embryonic remnants of the notochord in axial skeleton. "These mutations affect various subunits of the SWI/SNF chromatin remodeling complex, with ARID1A being the most frequently mutated gene, followed by SMARCA4, ARID1B, ARID2, PBRM1, and SMARCB1, mutations we have found to be common in adult chordoma." (PMID 39941902, 2025).
clear cell renal cell carcinoma (1 paper, 2020). "The patients belonging to C2 subclass showed the highest mutation frequency of ARID2 which was related to the efficacy of checkpoint blockade immunotherapy in clear cell renal cell carcinoma." (PMID 33680932, 2020).
colon cancers (1 paper, 2022). "Notably, we observed that mutations in KRAS, PIK3CA, CREBBP, FAT1, PKHD1, ARID2, and POLE were specifically enriched in right-site colon cancers in both our cohort and the validation cohort." (PMID 36439454, 2022).
cutaneous squamous cell carcinoma (1 paper, 2021). "Of note, another member of the SWI/SNF chromatin remodeling complex, ARID2, was also implicated as a tumor suppressor gene in cutaneous squamous cell carcinoma." (PMID 34272401, 2021).
eosinophilic disorders (1 paper, 2025).